CD4 (CD4 molecule)
Diseases named in the same sentence as CD4 in open-access papers (continued):
Sharing a sentence is not in itself a finding about the gene and the disease.
colitis (continued). "The induction of colitis by Rap1-deficient CD4+ effector/memory T cells suggests that the removal of constraining effect by Rap1-GDP on α4β7 is sufficient for homing of these pathogenic T cells into colon lamina propria (LP)." (PMID 32764635, 2020). "SHP-2 deficiency in CD4 T cells was found to augment colitis and reduced the incidence of colitis-associated colorectal cancers." (PMID 33425916, 2020). "Due to the biased expression of JunB in intestinal Tregs and observed weight loss in KO animals (a common manifestation of colitis), we evaluated CD4+ T cells for evidence of colonic cytokine dysregulation." (PMID 32296416, 2020). "Btk deficiency alleviated colitis and led to impaired CD4+ T-cell accumulation and inflammation in the spleen, draining LNs and lamina proper lymphocytes." (PMID 31431692, 2020). "The second reason is that although DSS-induced intestinal damage can happen in CD4 T cell depletion/deficient condition, the severity of colitis was dramatically decreased in Rag-1 KO mice compared with that in WT mice." (PMID 32183814, 2020). "We utilized a well-established mouse model of colitis in Rag1-deficient mice, which was induced by adoptive transfer of normal CD4+CD45RBhigh T cells." (PMID 30971739, 2019). "In contrast, unrestrained microbiota-triggered CD4+ Th1/Th17 cells cause inflammation in the T cell transfer colitis model." (PMID 31276514, 2019). "Insights into a possible T-cell intrinsic mechanism underlying exacerbated colitis came from our initial observation that CD4+ Th cells and CD8+ cytotoxic T cells in Asc−/− mice exhibited a significantly more activated phenotype than in WT mice." (PMID 31379813, 2019). "Colitis was induced in recombinase activating gene-1 deficient (Rag1-/-) mice injected with syngeneic CD4+CD62L+ naïve T cells." (PMID 31212794, 2019). "Differentiation/expansion of donor (Wild-type)-derived naïve (CD4+CD45RBHi) T cells in immune-deficient recipient (Rag−/−; scid/scid mice) induces transmural colitis with severe inflammation within small bowel." (PMID 31847438, 2019). "A recent study reported that AHCC® supplementation (75 mg/day) improved lymphocyte-driven colitis in recombination activating gene 1- (RAG-1-) deficient mice transferred with CD4+CD62L+ T cells." (PMID 31930148, 2019). "In a mouse model of colitis, selective ERα deficiency in CD4+ T cells inhibited IL-17A and IFNγ production from Th17 and Th1 cells, respectively, in the mesenteric lymph nodes as well as decreased Th17 and Th1-mediated inflammation in the gut." (PMID 31849948, 2019). "Adoptive transfer of IL-35-deficient Treg cannot cure CD4+CD45RBhi-induced murine colitis, whereas adoptive transfer of iTR35 generated in vitro can significantly improve the intestinal inflammation." (PMID 31886308, 2019). "In an animal colitis model, abrogation of IFN-γ in the CD4+ CD45RBhi/Rag−/− transfer model potently prevents the development of colitis; T-bet-deficient CD4+CD45RBhi cell cannot induce the colitis in Rag−/− recipients." (PMID 31886308, 2019). "In summary, the Mbd2−/− mouse is highly susceptible to DSS‐induced colitis, at least in part, due to the loss of Mbd2 function specifically within the CD4+ cells and loss of appropriate regulation of the pro‐inflammatory cytokine Ifng." (PMID 29603746, 2018). "While RAG-deficient (RAG2−/−) recipients of CD4+ T cells suffered from severe colitis with weight loss and high-grade intestinal inflammation, co-transfer of Keap-deficient CD11b+Gr-1+ cells markedly reduced loss of weight and intestinal inflammation." (PMID 30034396, 2018). "It was therefore surprising that despite the increased inflammation observed in mice harboring a PTPN11 deficiency in CD4+ T cells, mice were protected against colitis associated cancer." (PMID 30429852, 2018). "As expected, colitis induced by CD4+CD45RBhigh T cells in immune-depleted mice was associated with a significant increase in Th17 genes, IFNG, IL10 as well as S100A8 and S100A9 (data not shown)." (PMID 30405600, 2018).
colitis (continued). "Was-deficient innate immune cells were also suggested to exacerbate colitis after the observation that the transfer of WT naïve CD4 T cells in Was/Rag1 double-deficient mice induced a more severe colitis compared to their transfer into Rag1-deficient mice." (PMID 30410494, 2018). "For this purpose, colitis was induced in Rag1−/−Ifng+/+ or Rag1−/−Ifng−/− mice by adoptive transfer of IFNγ-sufficient or -deficient CD4 CD45RBhi T cells." (PMID 29416538, 2018). "There is also evidence suggesting that neutralization of IL-17 spontaneously causes dextran sulfate sodium-induced colitis and that IL-17R-deficient T cells accelerate gut inflammation in a CD4+ T-cell-mediated transfer model of colitis." (PMID 29892286, 2018). "We have previously shown that a subset of highly pathogenic memory-like CD4+ T cells survives and drive colitis in the Gimap5sph/sph mouse." (PMID 29382851, 2018). "Accordingly, transfer of Was-deficient CD4+ T cells into Rag2-deficient mice is sufficient to induce colitis." (PMID 30410494, 2018). "We then divided the splenic IL-10-producing Foxp3neg CD4+ T cells, which promoted colitis when transferred as one population in Rag1 deficient mice, into CIR rich and CIR poor cells and tested their pathogenicity in vivo." (PMID 30575716, 2018). "Previous study has reported different pathogenic effector cells for cholangitis and colitis as CD4+ T cells responsible for colitis and CD8+ T cells responsible for cholangitis." (PMID 29868034, 2018). "Our results also show that CD4+ T cell-specific conditional deletion of HDAC2 exacerbates colitis and EAE, and this is associated with elevated IL-17 expression." (PMID 30375383, 2018). "The loss of PTPN2 has been shown to alter CD4+ T cell differentiation, impacting disease severity in multiple murine colitis models." (PMID 30429852, 2018). "This correlates with inhibition of pathogenic activity in CD4+ T lymphocytes in intestinal lamina propria (LP), and decreased susceptibility to Th1-mediated colitis in mice overexpressing GILZ." (PMID 30083167, 2018). "The transfer of PTPN22−/− naïve CD4+CD45RBHI T cells into an immune-deficient recipient resulted in a more severe colitis phenotype, characterized by rapid weight loss and decreased survival." (PMID 30429852, 2018). "Here we demonstrate that macrophage specific deletion of WASP is sufficient to drive enhanced expression IL-1β and IL-23, which promotes generation of pathogenic IL-17+IFN-γ+ CD4+ T cells and colitis." (PMID 29725003, 2018). "Colitis was induced in Rag1−/− mice by administration of CD4+CD25− T cells, leading to body weight loss, rectal prolapse and diarrhea." (PMID 29386580, 2018). "Deficient production of PGE2 due to deletion of mPGES-1 in transferred T cells reduces colitis in association with developing CD4+ cells expressing high levels of RORγt." (PMID 30619314, 2018). "In fact, wild-type Tregs controlled colitis induced by the transfer of naïve CD4+ T cells into Rag1−/− mice, while TNFR2-deficient Tregs did not." (PMID 29541073, 2018). "In the T cell transfer colitis model, the transfer of naïve PTPN2−/− CD4+ T cells resulted in an earlier onset of disease, as well as an increased in weight loss, spleen weight and macroscopic signs of colitis." (PMID 30429852, 2018). "We have reported CD8+ T cells, particularly IFN-γ+ CD8+ T cells are pathogenic cells for cholangitis and CD4+ T cells for colitis." (PMID 29868034, 2018). "The most overt phenotype of our Cnb1CD4 mice was severe colitis associated with the vigorous expansion of effector CD4+ T cells in the intestine." (PMID 29515579, 2018). "In the present study, we further characterized an antiproliferative effect of DX5+NKT cells on colitis-associated CD4+CD62Lhigh cells." (PMID 30364054, 2018).
colitis (continued). "In a Th1-mediated CD model (CD45RB model) that is induced by the adoptive transfer of naïve CD4+ T cells into a immune-deficient host, both T cell-derived and NK cell-derived IL-22 contributed for the suppression of colitis." (PMID 29075900, 2018). "CD4+ T-cell depletion or T-bet/IFN-γ deficiency protects against the development of colitis induced by CS." (PMID 29163466, 2017). "Intestinal infections with the parasitic nematode H. polygyrus are known to expand CD4+ Foxp3+ Tregs and lead to chronic inflammation in susceptible mouse strains; two features that are considered to promote carcinogenesis in colitis-associated colon cancer." (PMID 28938014, 2017). "IFN-gamma and IL17A co-expression is thought to identify pathogenic CD4+ T cells in mouse colitis models, so we assessed their co-expression in E coli−reactive memory CD4+ T cells." (PMID 28782508, 2017). "Murine PHLPP1-deficient Treg cells are unable to protect against colitis induced by naive CD4+ T-cell transfer." (PMID 27477328, 2017). "In this study, we took advantage of mice with SHP2 deficiency in CD4+ T cells and two murine disease models, i.e., acute colitis and colitis-associated colon carcinoma." (PMID 27935860, 2017). "Mice either lacking Blimp-1 specifically in T cells or reconstituted with Blimp-1-deficient fetal liver cells develop progressive colitis or a lethal wasting disease with increased effector CD4+ and CD8+ T lymphocyte infiltration." (PMID 28732506, 2017). "Experiments using CD4+ T-cell or CD8+ T-cell depletion showed that the CD4+ T cell is a major cell subset causing CS-induced colitis, and other cells such as CD8+ T cells also have a role in this process." (PMID 29163466, 2017). "We examined the effect of Ccdc88b mutation on the capacity of naïve CD4+ T cell (CD4+CD45RBhi cells,) to induce colitis upon adaptive transfer into lymphopenic mice." (PMID 29030607, 2017). "Colitis caused by transfer of WT CD4+CD45RBhi T cells in severe combined immunodeficiency (SCID) mice shares many features with human IBD." (PMID 29059189, 2017). "Oral AJM300 also significantly reduces the histopathological severity of colitis in the murine model of the adoptive transfer of IL-10 deficient CD4+ T cells." (PMID 28690543, 2017). "While WT Treg cells efficiently prevented possible intestinal inflammation mediated by IL-15Rαko naive CD4+ T cells, the mice injected with IL-15-deprived Treg and WT CD4+ T cells demonstrated significant body weight loss and symptoms of colitis." (PMID 26964669, 2016). "Galectin-4 was demonstrated to exacerbate intestinal inflammation by directly stimulating the CD4+ T cells to produce IL-6 on TCR mutational colitis model." (PMID 27017379, 2016). "In this study, we confirmed that chronic exposure to psychological stress exacerbated colitis of Tcra-/- mice, which was associated with severe CD4+ TCRβdim T cell infiltration in the colonic mucosa." (PMID 27500935, 2016). "Taken together, our data clearly show that TNFR2 expression is required for the proliferative expansion of Teff cells as well as the development of pathogenic Th1 responses in mouse model of colitis induced by transfer of naive CD4 T cells." (PMID 27601345, 2016). "TNBS-mediated colitis is mainly T cell dependent and CD4+T cells are dominantly involved in the pathogenic process." (PMID 26728323, 2016). "More T cell proliferation marker of CD25 expression in CD4+ T cells was induced in mesenteric lymph nodes of iNOS deficiency mice which Citrobacter Redentium induced colitis than that in WT control mice." (PMID 27556858, 2016). "This idea is supported by our data presented in this study, which clearly indicate that TNFR2 expressed by pathogenic CD4 cells is required for the development of full-fledged colitis in a mouse model." (PMID 27601345, 2016). "Since pathogenic CD4 T cells drive disease progression in AdTr-colitis, colonic sections were stained for a T cell marker (CD3)." (PMID 26880890, 2016).
colitis (continued). "As expected, transfer of naïve CD4 T cells alone caused severe colitis characterized by gradual weight loss, inflammation in the colonic mucosa, splenomegaly and shortened colon length." (PMID 26892542, 2016). "Taking into account that IL-15-deficient mice developed severe colon inflammation despite the presence of Treg cells among the adoptively transferred CD4+ T cells, we investigated the fate of the transferred Treg cells in IL-15-deficient mice with colitis." (PMID 26964669, 2016). "We therefore examined the possibility that the conversion of naïve CD4 cells into induced Tregs (iTregs) contributed to the reduction in colitis induced by TNFR2-deficient cells." (PMID 27601345, 2016). "Previously we and others showed that Th1 cells were responsible for the pathogenic effect of CD4 Teff cells in this experimental colitis model." (PMID 27601345, 2016). "Smad2/Smad3 double deficient mice develop fatal inflammatory diseases with reduction in Foxp3 expression in CD4+ T cells while Smad2 deficiency make mice susceptible to DSS induced colitis." (PMID 28003811, 2016). "To confirm that IL-17A/IL-22 produced by CD4+ T cells are indeed pathogenic factors in Tbx21−/− driven T cell transfer colitis, we stimulated intestinal epithelial cells with supernatant of IL-23-activated WT and Tbx21−/− T cells." (PMID 27193261, 2016). "Animals adoptively transferred with S100a4Gfp/Gfp or S100a4+/+ CD45RBhigh CD4+ T cells developed equally colitis as assessed over time by the loss of body weight." (PMID 26734465, 2015). "RAG-1−/− mice transferred with either CD4+CD45RBhigh cells alone (control group) or together with TCRγδ+LAP− cells began to exhibit signs of colitis as measured by body weight loss at 5 weeks after transfer." (PMID 26644347, 2015). "Together, these data suggest that Rap1-GDP restrains rolling behaviours via phosphorylation of ERM proteins, which inhibited the onset of colitis by suppressing the trafficking of CD4+-pathogenic T cells into the colon." (PMID 26634692, 2015). "Compared to NOD2-deficient mice, NOD2xTLR2 double-deficient mice showed attenuated ovalbumin-induced colitis with impaired CD4+ T cell infiltration into the mucosa and reduced production of IFN-γ in MLN cells." (PMID 26067254, 2015). "We examined the contribution of CD169+ macrophages in the development of another colitis model, T-cell-transfer colitis, which is induced by the adoptive transfer of WT naive CD4 T cells into lymphocyte-deficient mice." (PMID 26193821, 2015). "These cells have been shown to support colitis-associated cancer development by preventing the anti-tumor immune responses via inhibition of tumor-specific CD4+ cells and cytotoxic T lymphocytes." (PMID 26109431, 2015). "By contrast, mice that received WT naïve CD4+ T cells together with Ezh2-deficient Treg cells developed colitis and lost weight, suggesting that Ezh2-deficient Tregs were functionally defective." (PMID 26090605, 2015). "When colitis was induced in Rag1-deficient mice, recipients of either wild type or Tpl2−/− naïve CD4 T cells experienced similar weight loss kinetics." (PMID 25781948, 2015). "Colitis was induced in Rag1−/− mice by administration of CD4+CD25− T cells, leading to 20–30% weight loss, rectal prolapse and diarrhoea." (PMID 25695215, 2015). "Our data argue against any direct attenuating effects on inflammatory CD4+ T-cells but, in contrary, show that β2i/MECL-1&β5i/LMP7-deficiency enhances CD4+ T-cell-mediated inflammation in T-cell transfer-induced colitis." (PMID 24740379, 2014). "This injection of naive CD4+CD25−CD62L+ T cells led to the development of colitis, which has been proven to result from a deficiency in Treg cells." (PMID 25313594, 2014). "Enhanced colitis scores were associated with enhanced numbers of total splenic CD4+ T-cells, enhanced frequencies and numbers of iTregs and enhanced IL17 production." (PMID 24740379, 2014).
colitis (continued). "Co-transfer of CD4+ CD45RBlow cells, which contain Tregs, blocked CD4+ CD45RBhi cell-induced pathogenesis; however, colitis by A2AR-deficient CD4+ CD45RBhi cells was resistant to the preventive effect of CD4+ CD45RBlow cell co-transfer." (PMID 25071765, 2014). "Surprisingly, β2i/MECL-1−/−β5i/LMP7−/− CD4+ T-cells also caused colitis, both in RAG1−/− and RAG1−/−β2i/MECL-1−/−β5i/LMP−/− mice." (PMID 24740379, 2014). "Within the DSS model, increases in mucosal CD4+ T cells occur in a dose dependent fashion such that with 5% DSS induced colitis is associated with significantly more CD4+ T cells compared to 3% DSS colitis." (PMID 24712338, 2014). "Unexpectedly, Rag1−/− recipients of the CXCR6− subset exhibited progressive body weight loss with clinical symptoms of colitis to a similar extent as the recipients of splenic CD45RBhigh naïve CD4+ T cells." (PMID 23840334, 2013). "To quantitatively define the distribution of BM-derived CD11c+ DC and CD4+ T cells in our colitis-associated colorectal cancer model, we isolated the tumor-infiltrating cells from the mouse tumor tissues and performed FACS analysis." (PMID 24040017, 2013). "In this study, we established combined BM transplantation and a colitis-associated colorectal cancer model to define the distribution of BM-derived endothelial cells, CD11c+ DC and CD4+ T cells in tumors." (PMID 24040017, 2013). "These Th2-derived CD4+CD8α+ T cells were recovered from the primary recipient mice and subsequently transferred into secondary immunodeficient hosts, where they prevented colitis development induced by pathogenic CD4+CD45RBhi T cells." (PMID 23844100, 2013). "In contrast, PSGL-1 deficient CD4+ T cells were able to induce colitis in the transfer colitis model as used here." (PMID 23630623, 2013). "This phenotype switch is associated with protection from CD4+ T cell-induced colitis during adoptive transfer experiments in mice." (PMID 23592971, 2013). "The transfer of CD69-deficient CD45RBhigh CD4 T cells into RAG-deficient hosts induced accelerated colitis." (PMID 23785429, 2013). "Experimental colitis, induced by adoptive transfer of IL-17-secreting CD4+ T cells to Rag-deficient mice, can be suppressed by the co-transfer of IL-10-secreting CD4+ T cells." (PMID 23755052, 2013). "The transfer of CD69-deficient CD45RBhigh CD4 T cells into RAG KO hosts induced accelerated colitis." (PMID 23785429, 2013). "Body weight loss resulting from colitis was observed in Rag2-/- mice that received a transfer of naïve CD4+T cells." (PMID 24058613, 2013). "We also discovered a new CD4+ CD11c+ DC subset (0.34 vs 1.64) in our colitis-associated colorectal cancer model." (PMID 24040017, 2013). "CD4+ T cells recognizing antigens derived from the commensal microflora cause colitis under lymphopenic conditions." (PMID 22384106, 2012). "Previously, we have demonstrated that deletion of the gene responsible for LTA biosynthesis in L. acidophilus NCFM diminishes this bacterium's capacity to stimulate the immune system; thereby suppressing pathogenic CD4+T cells in induced colitis." (PMID 22423982, 2012). "In CCR5 deficient mice a more CD4+ Th2 cell activation pattern was seen in colitis in contrast to CCR5 wild type mice." (PMID 22348061, 2012). "Transfer of naïve CD8+ T cells into syngeneic RAG-deficient mice results in severe colitis, similar to that seen after transfer of naïve CD4+ T cells." (PMID 22082127, 2011). "When cells from these mice are transferred to NOD/scid recipients, the pathogenic activated CD4+ T cells infiltrate the colons and cause severe colitis accompanied by significant body weight loss." (PMID 19172487, 2009). "In the transfer model of colitis developing in CD4+CD45RBhigh T cell reconstituted immune-deficient SCID mice we have shown that the presence of normal gut microbiota enhances a functional potency of the Treg population." (PMID 18990206, 2008).